TLR9 (toll like receptor 9)
Diseases named in the same sentence as TLR9 in open-access papers (continued):
Sharing a sentence is not in itself a finding about the gene and the disease.
Sepsis (continued). "Hence, it is possible that melatonin also provides protections against sepsis through suppressing TLR9-mediated inflammation, which requires to be further investigated." (PMID 30349079, 2018). "In addition, we investigated an inhibitory CpG ODN designed as a TLR9 antagonist to block immunostimulatory CpG ODN to treat sepsis and lupus nephritis." (PMID 26907260, 2016). "Inhibition of these responses by both Mito-Vit-E and TLR9 inhibitor ODN-I provides clear support of our hypothesis that sepsis stimulates a mtROS-mtDNA-TLR9 inflammation pathway in cardiomyocytes." (PMID 26448624, 2015). "We next examined whether sepsis alters the expression of TLR9 and related response factors, such as myeloid differentiation primary response protein MYD88 and IL-1R-associated kinase–4 (IRAK4)." (PMID 26448624, 2015). "With respect to the importance of effective inhibition of TLR signaling in sepsis, the aim of the present study was to test different TLR9 inhibitors (H154-thioate, IRS954-thioate, and chloroquine) for their effectiveness in protecting the cardiovascular system during systemic inflammation." (PMID 23690658, 2013). "The authors proposed that targeting TLR9 could be a useful approach for the management of cardiovascular dysfunction in severe sepsis patients." (PMID 24302927, 2013). "Therefore, TLR9 can be regarded as a central receptor for inflammatory response in any kind of sepsis." (PMID 23690658, 2013). "Bacterial DNA released during infection is a MAMP, and exuberant activation of TLR9 may participate to the sepsis pathophysiology." (PMID 24302927, 2013). "However, the focus of the present study was septic heart failure in polymicrobial sepsis and the implication of TLR9 in the progression of this disease." (PMID 23935245, 2013). "Thus, pharmacological intervention of blocking TLR9 signalling shows promise as a new approach for treating polymicrobial sepsis." (PMID 23935245, 2013). "Taken together our data give for the first time evidence that TLR9 is a key element in the development of vascular dysfunction during polymicrobial sepsis and might be a pharmacological target." (PMID 22970242, 2012). "Our results also indicated that tag SNPs of TLR2, TLR4, TLR9, and MyD88 did not represent major risk factors for sepsis development." (PMID 21219635, 2011). "No haplotypes in TLR2, TRL4, TLR9, and MyD88 were associated with sepsis risk in this study (data not shown)." (PMID 21219635, 2011). "To test this hypothesis, we conducted a case control study using a tag SNP approach to investigate the association of variants in TLR2, TLR4, TLR9, MyD88, and TOLLIP with susceptibility to sepsis in the Chinese Han population." (PMID 21219635, 2011). "Taken together, those data suggest that medication able at blocking TLR9 maturation or signalling could be of interest in sepsis." (PMID 20396414, 2010). "It has been demonstrated that activation of TLR9 signaling pathway could be deleterious in a murine model of sepsis." (PMID 20949109, 2010). "Our data suggest that hemorrhagic shock induces ex vivo unresponsiveness to TLR9 agonists in cDCs by an unknown mechanism, which was apparent during the subsequent sepsis." (PMID 20949109, 2010). "In addition, IFNα secretion by PDCs after stimulation with TLR9-activating CpG ODN was significantly decreased in sepsis, and this reduction exceeded (more than twofold) the decrease in PDC counts both at baseline and after 28 days." (PMID 19604380, 2009). "However, the mRNA expression of TLR-9 was markedly increased after 24 h of sepsis." (PMID 40076895, 2025). "Together, these results underscore the critical role of preclinical models in identifying mechanistic elements (i.e., RBC TLR9) that may drive differential host inflammatory responses and identify RBC TLR9–mediated DNA regulation as a potentially treatable trait in sepsis." (PMID 39666381, 2024). "Therefore, inhibition of TLR9 activation represents a potential strategy for treating human sepsis." (PMID 37662481, 2023).
Sepsis (continued). "Thus, depending on the disease stage, activation of TLR9 in response to the self-DNA during different infections, including sepsis, may have therapeutic potential." (PMID 33643304, 2020). "Immune paralysis in sepsis may be triggered by activation of TLR9 by mtDNA." (PMID 31205588, 2019). "Therefore, the association between TLR-9 gene rs187084 polymorphism and relevant diseases has been widely investigated, such as systemic lupus erythematous (SLE), OA, malaria, and sepsis." (PMID 28916728, 2017). "Therefore, suppressive oligodeoxynucleotides and anti-TLR9 treatment, which minimize or counteract the impact of extracellular mtDNA, may be promising therapies for sepsis treatment." (PMID 27589725, 2016). "Although TLR9 deficiency protects against sepsis-induced AKI, no role for TLR9 could be established in a model of renal IRI or moderate renal IRI (this study)." (PMID 26361210, 2015). "The effect of TLR9-dependent systemic inflammation as well as organ dysfunction seems to be dose dependent as a low concentration (0.25 nmol/g) can serve as a mild stimulus for cardiac preconditioning, whereas higher concentrations in the range from 0.5 to 1 nmol/g induce sepsis-like inflammation." (PMID 23690658, 2013). "In addition, we have shown that TLR9 stimulation is pivotal for vascular dysfunction during sepsis." (PMID 23935245, 2013). "Furthermore, it has been shown that TLR9 antagonism attenuates sepsis-induced kidney failure." (PMID 22970242, 2012). "Three heavily studied TLRs in the context of sepsis include TLR2, TRL4, and TLR9, which are present in lymphocytes and macrophages." (PMID 39968295, 2025). "During sepsis, cfDNA primarily triggers inflammatory responses by activating specific PRR pathways, including TLR9-myeloid differentiation primary response 88 (MyD88), AIM2 inflammasome, and cGAS-STING pathways." (PMID 41327452, 2025). "In a murine model of polymicrobial sepsis, we show that RBCs captured microbial DNA during sepsis and that RBC Tlr9–mediated DNA delivery drove hyperinflammation." (PMID 39666381, 2024). "In sepsis, mitochondrial debris, including mtDNA, contributes to AKI, with overproduction of renal mitochondrial superoxide via TLR9, while DNase treatment diminishes both AKI and renal mitochondrial superoxide." (PMID 36757801, 2023). "Despite debate on the use of hydroxychloroquine in sepsis, especially in acute respiratory distress syndrome from Coronavirus (COVID-19) infection, there might be some sepsis conditions that are beneficial from TLR-9 inhibition and bacterial DNA neutralization." (PMID 35163830, 2022). "From all animal models, we demonstrated the gut translocation of bacteria-free DNA in sepsis with LPS-bacterial DNA synergy, possibly through the simultaneous TLR-4 and TLR-9 activation on macrophages." (PMID 35163830, 2022). "In a mouse sepsis AKI model, we previously showed that circulating cfDNA, a DAMP, increased mitochondrial superoxide (mtROS) production via a TLR9-dependent inflammatory response." (PMID 33651717, 2021). "Obviously, microbial structures, such as LPS or CpG, flood the host system during sepsis, and are able to polyclonally activate B cells via their appropriate receptors (TLR4 or TLR9)." (PMID 32425951, 2020). "On the other hand, TLR9 activation in the airways in mice using high dose CpG-motifs, does lead to inflammation in the airways, ARDS, and sepsis." (PMID 33519463, 2020). "It is important to note that mtDNA cannot only be sensed by NLRP3, but also by multi-signaling pathways, such as TLR9 and cyclic GMP-AMP synthase, to induce the progression of sepsis." (PMID 33324236, 2020). "For example, TLR9 activation in response to the circulating mtDNA induces sepsis-induced acute kidney injury (AKI) and splenic apoptosis during polymicrobial sepsis." (PMID 33643304, 2020). "Toll-like receptor 9 (TLR9) is located on the lysosomal membrane and involved in cancer, sepsis and other diseases." (PMID 32612147, 2020).
Sepsis (continued). "There were important hemodynamic differences applied by Echo-Doppler technology related to TLR3−/− and TLR9−/− mice after CLP, suggesting that both receptors have important but different contributions to cardiac performance in response to sepsis." (PMID 30364002, 2018). "It was reported that toll-like receptor 9 (TLR9) is involved in multiple organ failure, including acute kidney injury (AKI) and sepsis-induced cardiac inflammation." (PMID 30092777, 2018). "Animal models of sepsis-induced cardiac inflammation show that at least partially mtDNA–TLR9–RAGE pathway is involved and activated but can be inhibited by a TLR9 inhibitor." (PMID 30013565, 2018). "Previous studies showed that polymicrobial sepsis in mouse experimental peritonitis model induced by caecal ligation and puncture (CLP) was TLR9-dependent." (PMID 30349079, 2018). "In this respect, in a mouse model of sepsis, CQ administration induced decreased expression of TLR9 in the spleen, which was associated with increased survival and reduction of renal injury; interestingly, the same effect was evident in the absence of TLR9 (TLR9-deficient mice)." (PMID 30034390, 2018). "Indeed, mtDNA acts as a Danger-Associated Molecular Pattern (DAMP) in animal models of sepsis and triggers both intracellular inflammasome activation (through NOD-like receptor family, pyrin domain containing 3, NLRP3) and remote organ injury (through Toll-like receptor 9 (TLR9) binding)." (PMID 28589148, 2017). "KB possesses anti-inflammatory activity, as demonstrated by its ability to inhibit the inflammatory response in mouse macrophages, rescue mice from heat-killed E. coli-induced sepsis and prevent the upregulation of TLR4 and TLR9 expression." (PMID 25667619, 2015). "Both Mito-Vit-E and TLR9 inhibitor OND-I repressed LPS-induced up-regulation of MYD88, RAGE, ASC, activated caspase 1 and IL–1β, confirming that sepsis induces a mtROS dependent mtDNA-TLR9 pathway in cardiomyocytes." (PMID 26448624, 2015). "Hence, drug inhibitors of TLR9 may have therapeutic potential in human sepsis." (PMID 24302927, 2013). "Collectively, these findings suggest that TLR9 could be a potential therapeutic target for treating SAE, as well as a predictive biomarker for treatment outcomes in sepsis." (PMID 39861004, 2025). "We and others previously showed mice lacking TLR9 or treated with a TLR9 inhibitor were protected from sepsis mortality and AKI, and a TLR9 ligand mtDNA was released during early sepsis and contributes to cytokine production and AKI." (PMID 36757801, 2023). "Administration of the TLR9 antagonist ODN-2088 has been demonstrated to be an ideal treatment for several diseases, such as spinal cord injury, cerebral ischemia/reperfusion injury, liver injury and sepsis." (PMID 37365190, 2023). "It has been previously reported that CQ could protect against liver damage in sepsis-induced acute kidney injury by suppressing the expression of the inflammatory cytokines TNF-α and IL-10 through TLR9 inhibition." (PMID 35346242, 2022). "In sum, the activation of TLR2, TLR4, TLR7, TLR9 and NLRP3 are almost certainly maintained by DAMPs in severe COVID-19, ALI/ARDS and sepsis and may need to be therapeutically addressed." (PMID 33672738, 2021). "Flow cytometry analysis further revealed that downstream effectors of TLR9, including IRF3, MyD88, and TRAF3, were elevated in all of the sepsis patients compared with the normal donors, and was correlated with improved prognosis in patients with sepsis." (PMID 31534550, 2019). "While these data are preliminary, they indicate that TLR absence reduces plasma levels of proinflammatory cytokines, suggesting that events that “drive” the adverse consequences of sepsis are negatively affected by absence of TLR3 or TLR9." (PMID 30364002, 2018).
Sepsis (continued). "We measured the levels of proinflammatory cytokines in cardiac tissue using heart homogenate to study how the absence of TLR3 or TLR9 affects the appearance of proinflammatory cytokines in the heart tissue after sepsis." (PMID 30364002, 2018). "Septic TLR9−/− mice exhibited lower inflammatory cytokines release and higher survival compared with wild-type mice, indicating that inhibition of TLR9 is a potential therapeutic strategy for sepsis." (PMID 26907260, 2016). "However, this study demonstrates for the first time that TLR9 and CD14 play a major role in the development of vascular dysfunction in polymicrobial sepsis." (PMID 22970242, 2012). "In the polymicrobial sepsis model, we observed a marked reduction in cytokine production in the plasma and spleen, alongside increased organ dissemination in mice that lacked erythrocyte Tlr9." (PMID 39666381, 2024). "Moreover, TLR9 inhibition by gene deletion, small interfering RNA, and chemical inhibitor (chloroquine) has been shown to reduce the excessive inflammation and mortality of CLP-induced sepsis, a clinically relevant model of polymicrobial sepsis." (PMID 37662481, 2023). "However, in CLP-induced sepsis, whether TST-SSM protection is fully dependent on TLR9-mediated signaling remains unclear." (PMID 37662481, 2023). "The authors showed that endogenous mtDNA, which may not originate from a bacterial source, could be the primary TLR9-dependent DAMPs contributing to AKI during polymicrobial sepsis." (PMID 36010680, 2022). "To determine whether NET-induced Mφ pyroptosis following sepsis is a specific receptor-dependent event, we isolated BMDM from WT, RAGE−/−, TLR4−/−, and TLR9−/− mice, and then treated the cells with NETs (or the medium supernatant of the unstimulated PMN as a control) for 12 h." (PMID 29789550, 2018). "Moreover, the lower levels of complement C5a and extracellular histones in plasma during sepsis in TLR3−/− and TLR9−/− mice suggest that these biological markers may act as a downstream effector of TLR3 and TLR9 signaling." (PMID 30364002, 2018). "Protection of TLR9−/− mice after CLP can be attributed to a greater number of peritoneal DCs and granulocytes than those in WT mice, suggesting that TLR9 blockade may be a useful strategy for the treatment of human sepsis." (PMID 29075648, 2017). "Supporting the hypothesized role of TLR9 pathway in sepsis, our results showed an increase in myocardial expression of MYD88 and RAGE, both of which function as downstream TLR9 factors, as well as a formation of physical interaction between RAGE and its ligand TFAM." (PMID 26448624, 2015). "Whether its actions in polymicrobial sepsis are TLR9 specific or nonspecific has still to be elucidated." (PMID 20396414, 2010). "However, evidence that CLP performed in the active phase (ZT19) led to higher mortality compared to the inactive phase (ZT7) in 6-12-week-old C57BL/6 TLR9−/- mice (80 vs. 30%, mixed sex) suggests that TLR9 is not involved in the circadian dependency of sepsis mortality per se." (PMID 39968295, 2025). "However, our research team is targeted at patients with common infection, and the severity of the disease is far less than that of severe sepsis, so the amount of mtDNA bound to TLR9 is small, which is not enough to affect red blood cells and TLR9 on their surfaces." (PMID 40046178, 2024). "In addition, cytosolic mtDNA fragments also stimulate inflammation signals like TLR9 and cyclic GMP–AMP synthase, to aggravate the inflammatory response of sepsis, which emphasizes the significant role of autophagy in clearing DNA during the development of sepsis." (PMID 33324236, 2020). "In a mouse model of polymicrobial sepsis, RBC-bound bacterial DNA was elevated in WT but not in erythroid TLR9-deleted mice." (PMID 38746470, 2024). "In a mouse model of polymicrobial sepsis, RBC-bound bDNA was elevated in WT mice but not in erythroid Tlr9–deleted mice." (PMID 39666381, 2024).
Sepsis (continued). "Murine models of sepsis-induced ALI mimic TLR3, TLR4, TLR7 and NLRP3 activation but, unlike the human disease, also activate TLR2 and TLR9." (PMID 33672738, 2021). "We extended the studies to determine how absence of TLR3 (frames (a) and (b)) or TLR9 (frames (c) and (d)) in CLP mice affects sepsis-induced appearance of plasma proinflammatory cytokines." (PMID 30364002, 2018). "On the other hand, the myocardial expression of TLR9 itself and IRAK4, a factor downstream of TLR-MYD88, was not affected in the sepsis model we examined." (PMID 26448624, 2015). "Both allele and genotype distributions of the other 14 SNPs in TLR2, TLR4, TLR9, MyD88, and TOLLIP did not vary significantly between sepsis patients and healthy controls." (PMID 21219635, 2011). "In sum, all that can be said in general about innate activation in sepsis is that TLR2, TLR4, TLR5, TLR7 and NLRP3 can be, but are not necessarily, activated, while TLR9 may or may not be downregulated." (PMID 33672738, 2021).